HS3ST3A1 (heparan sulfate-glucosamine 3-sulfotransferase 3A1)
Description:
Sulfotransferase that utilizes 3'-phospho-5'-adenylyl sulfate (PAPS) to catalyze the transfer of a sulfo group to an N-unsubstituted glucosamine linked to a 2-O-sulfo iduronic acid unit on heparan sulfate. Catalyzes the O-sulfation of glucosamine in IdoUA2S-GlcNS and also in IdoUA2S-GlcNH2. The substrate-specific O-sulfation generates an enzyme-modified heparan sulfate which acts as a binding receptor to Herpes simplex virus-1 (HSV-1) and permits its entry. Unlike HS3ST1/3-OST-1, does not convert non-anticoagulant heparan sulfate to anticoagulant heparan sulfate.
Synonyms: 3-OST-3A; 3OST3A1; 30ST3A1
Tractability: Small molecule: a structure with a bound ligand is known; it has a high-quality binding pocket. Antibody: UniProt predicts a signal peptide or a membrane-spanning region.
Gene: Protein-coding gene on chromosome 17 (13,494,032 to 13,601,929, reverse strand). Ensembl gene ENSG00000153976.
Subcellular location: Golgi apparatus membrane
Subcellular location (Human Protein Atlas): Microtubules
Pathways (Reactome):
Metabolism: HS-GAG biosynthesis
Gene Ontology:
Molecular function: [heparan sulfate]-glucosamine 3-sulfotransferase activity; sulfotransferase activity
Biological process: glycosaminoglycan biosynthetic process; heparan sulfate proteoglycan biosynthetic process; branching involved in ureteric bud morphogenesis
Cellular component: Golgi membrane; membrane
Genetic constraint (gnomAD): Loss-of-function variants: 18 observed, 14.69 expected, observed/expected ratio (o/e) 1.23, 90% interval 0.84 to 1.77. The synonymous counts are far from expectation, so gnomAD's model fits this gene poorly and the ratio says little. Missense variants: 420 observed, 346.4 expected, observed/expected ratio (o/e) 1.21, 90% interval 1.12 to 1.31. Synonymous variants: 204 observed, 156.02 expected, observed/expected ratio (o/e) 1.31, 90% interval 1.17 to 1.47.
Homologues: Orthologues: macaque HS3ST3A1 (97% identical), dog HS3ST3A1 (90% identical), rabbit HS3ST3A1 (89% identical), pig HS3ST3A1 (88% identical), mouse Hs3st3a1 (83% identical), rat Hs3st3a1 (82% identical), chimpanzee HS3ST3A1 (82% identical), guinea pig HS3ST3A1 (78% identical), zebrafish hs3st3b1a (54% identical), zebrafish si:dkey-121b10.7 (54% identical), zebrafish hs3st1l2 (30% identical), Drosophila melanogaster sfl (25% identical), and 1 more. Paralogues in human: HS3ST3B1 (73% identical), HS3ST4 (55% identical), HS3ST2 (53% identical), HS3ST6 (52% identical), HS3ST5 (34% identical), HS3ST1 (31% identical), NDST1 (30% identical), NDST4 (29% identical), NDST2 (29% identical), NDST3 (29% identical).
Diseases named in the same sentence as HS3ST3A1 in open-access papers:
HS3ST3A1 is named in the same sentence as 16 diseases in open-access papers, as found by Europe PMC text mining. Sharing a sentence is not in itself a finding about the gene and the disease. The quoted sentences say what the papers report.
lung carcinoma (4 papers, 2020 to 2022). "Besides, HS3ST3A1 was found to be upregulated in lung cancer tissue compared with normal lung tissue and associated with the progression of lung cancer." (PMID 36590308, 2022). "Several studies also found that HS3ST3A1 was a novel tumor regulator and a good predictor of survival in both lung cancer patients and breast cancer patients." (PMID 36077687, 2022).
bladder cancer (1 paper, 2022). "Second, significantly altered miRNAs in recurrent bladder cancer were identified, with miR-154-5p showing the highest level of editing in recurrent bladder cancer and may up-regulate the expression levels of downstream targets HS3ST3A1, AQP9, MYLK, and RAB23." (PMID 36199571, 2022).
chondrosarcoma (1 paper, 2019). A malignant cartilaginous matrix-producing mesenchymal neoplasm arising from the bone and soft tissue. "Besides HS3ST2, an analysis of the methylation status of other genes encoding HS sulfotransferases in chondrosarcoma showed hypermethylation in proximal regions of the HS3ST1 and HS3ST3A1 genes." (PMID 31249810, 2019).
melanoma (1 paper, 2024). A malignant, usually aggressive tumor composed of atypical, neoplastic melanocytes. "A375 TFCP2 knockout human melanoma cells have decreased expression of HS3ST3A1 and HS6ST2 and increased expression of SULF1 and SULF2 what allowed the authors to state TFCP2 as a novel transcriptional regulator of HS biosynthesis." (PMID 39318629, 2024).
osteoporosis (1 paper, 2015). A condition of reduced bone mass, with decreased cortical thickness and a decrease in the number and size of the trabeculae of cancellous bone (but normal chemical composition), resulting in increased fracture incidence. "Although this study has thrown some light on the mechanism of HQSXD action, we failed to characterize the well-identified protein (e.g., HS3ST3A1) closely involved in osteoporosis." (PMID 26557149, 2015).
papillary thyroid cancer (1 paper, 2022). "To verify the cellular function of HS3ST3A1 and CAPN8, we transfected shHS3ST3A1 and shCAPN8 into papillary thyroid cancer cells BCPAP and TPC-1, which downregulation was detected by Western blot." (PMID 36590308, 2022). "In vitro, the downregulation of HS3ST3A1 and CAPN8 presented the inhibition of proliferation and invasion in papillary thyroid cancer cells." (PMID 36590308, 2022).
thyroid cancer (1 paper, 2022). "It is our study that collects LRRN4CL, HS3ST3A1, PCOLCE2, and CAPN8 all together for the first time and sets them as biomarkers related to TME in thyroid cancer, which might become potential candidate targets for TC immunotherapy." (PMID 36590308, 2022). "Furthermore, HS3ST3A1 and CAPN8 were highly expressed in thyroid tumor tissue, especially in tumors with LNM, and their downregulation can inhibit the proliferation and invasion of thyroid cancer cells." (PMID 36590308, 2022).
tumor (8 papers, 2016 to 2022). "RT-qPCR results indicated that the mRNA levels of HS3ST3A1 and CAPN8 were remarkably higher in tumor tissues compared with normal tissues." (PMID 36590308, 2022).
cancer (5 papers, 2018 to 2022). A tumor composed of atypical neoplastic, often pleomorphic cells that invade other tissues. "Previous research has linked aberrant expression of HS3ST3A1, AQP9, MYLK, and RAB23 to cancer formation, invasion, and prognosis." (PMID 36199571, 2022).
HS3ST3A1 also shares sentences with these, for which no sentence is quoted: breast carcinoma (3 papers); cognitive decline (1); glioblastoma (1); hepatocellular carcinoma (1); invasive breast ductal carcinomas (1); pancreatic cancers (1); thyroid tumor (1).